STAT3 (signal transducer and activator of transcription 3)
Diseases named in the same sentence as STAT3 in open-access papers (continued):
Sharing a sentence is not in itself a finding about the gene and the disease.
Stroke (continued). "Inhibition of S1P signaling preserves BBB integrity after ischemia by suppressing STAT3 activation; probucol shows promise as a stroke treatment." (PMID 40880849, 2025). "Specifically, IL6 signaling through the Janus kinase (JAK) and signal transducer and activator of transcription 3 (STAT3) pathway plays a major role in post-stroke inflammatory responses through the transcription of various inflammatory genes." (PMID 40362325, 2025). "STAT3 was found to be upregulated in astrocytes after stroke, but the role of STAT3 in astrocytes and its effect on neuronal synaptic remodeling are unclear." (PMID 40919080, 2025). "Our study demonstrated that the phosphorylation level of STAT3 was increased in astrocytes during the acute phase after stroke." (PMID 40919080, 2025). "The activation of specific Janus kinase-signal transducers and activators of transcription (JAK/STAT) signaling pathway such as JAK1/STAT3, by propofol has been reported to be neuroprotective in stroke." (PMID 40649310, 2025). "The ability of JB to modulate microglial polarization through JAK2/STAT3 inhibition presents a promising pharmacological approach for cerebral ischemia–reperfusion injury management in stroke therapy." (PMID 41254929, 2025). "Validation in GSE35338 and GSE137482 showed consistent upregulation of MCL1, TNFRSF1A, and STAT3 in stroke, supporting their role as candidate biomarkers." (PMID 41235394, 2025). "Among the JAK/STAT family members, activation of the JAK1/STAT3 pathway has shown anti-inflammatory effects in stroke." (PMID 40649310, 2025). "Our results showed that microbiota depletion triggered very low levels of several inflammatory signaling genes such as Myd88, IL-17ra, Edn1 and Stat3 in the ischemic hemispheres of MiD mice compared to MiS stroke mice." (PMID 40410847, 2025). "Collectively, these findings suggest that MCL1, TNFRSF1A, and STAT3 regulate PANoptosis and contribute to stroke progression." (PMID 41235394, 2025). "Gene expression of the proinflammatory M1 microglia marker Stat3 was significantly increased in NT stroke vs NT Sham (P < 0.05), whereas expression of Tnfa and Nos2 were not changed." (PMID 38886874, 2024). "In various stroke models, STAT3 inhibition can lessen brain injury and enhance neurological effects." (PMID 38384585, 2024). "The relationship between miR-155 and STAT3 was highlighted, suggesting a direct role of miR-155 in promoting post-stroke inflammation through the STAT3/JAK2 axis." (PMID 38920691, 2024). "In a rat stroke experiment, extracellular vesicles containing miR-124, released by microglia, targeted the STAT3 pathway to mitigate glial scar formation, demonstrating potential for addressing neuronal regeneration disorders post-stroke." (PMID 38143562, 2023). "The proangiogenic effect of IL-6 is closely associated with the early activation of angiogenesis-related gene transcription and STAT3 phosphorylation in the delayed phases after stroke." (PMID 36873773, 2023). "Several groups have reported that the JAK2/STAT3 pathway is activated in in vitro and in vivo experimental models of stroke." (PMID 36419252, 2023). "Nevertheless, the palmitoylation modification of STAT3 resulted from lipogenesis in reactive astrocytes after stroke need to be confirmed in further study." (PMID 37968698, 2023). "The impact of circ-STAT3 rs2293152 on the short-term prognosis of stroke appears to be mediated by the regulation of circ-STAT3 expression due to its influence on neuroinflammation processes following a neural lesion." (PMID 37241009, 2023). "Activation of the JAK/STAT3 pathway in stroke is well-documented and its inhibition is found to significantly reduce the inflammatory process." (PMID 35250546, 2022). "These latter studies are in line with our data, as we observed a phenotypic shift in favor of microglia/macrophage involved in inflammation resolution, which support the beneficial effect of reducing p-STAT3 after stroke." (PMID 35578342, 2022).
Stroke (continued). "In agreement with our findings, transcriptomic analysis of astrocytes has shown Stat3, Sp1, and Spi1 as the most significant transcription factors in stroke." (PMID 35250546, 2022). "There is still great research value for the four more meaningful stroke-related proteins (STAT3, MMP2, ESR1, TERT) in this study, and pointed out the direction for our further research." (PMID 36133785, 2022). "A recent study on non-erythropoietic mutant erythropoietin (MEPO) showed that increased STAT3 phosphorylation was involved in the neuronal protection provided by MEPO in stroke mice using the specific inhibitor AG490 to block JAK2/STAT3 activation." (PMID 35578342, 2022). "The JAK2/STAT3 pathway has been highlighted by in vitro and in vivo experimental stroke models, subsequently activating numerous genes responsible for many cellular functions in neural injury and repair." (PMID 35055089, 2022). "Since the role of STAT3 in stroke is also diverse and controversial, further studies are needed to explore the accurate action of STAT3 signaling in neuroprotective effect." (PMID 35173738, 2022). "A previous study demonstrated a protective role of STAT3 in stroke with pharmacological inhibition leading to increased infarct; however, such a study does not inform about which cell type(s) mediate this effect." (PMID 36293020, 2022). "In the rodent brain STAT3 is protective in stroke; pharmacological inhibition of STAT3, which is upregulated during reperfusion, results in increased infarct after middle cerebral artery occlusion (MCAO)." (PMID 36293020, 2022). "Endothelial STAT3 can have pro-angiogenic functions in paradigms other than stroke, where stimulation of ECs by vascular endothelial growth factor (VEGF) leads to STAT3-mediated angiogenesis and associated vascular permeability via canonical STAT3 signaling." (PMID 36293020, 2022). "A central role of JAK/STAT3 signaling in astrogliosis is well documented in several neurological conditions including stroke, AD, spinal cord injury, multiple sclerosis, and epilepsy." (PMID 34911575, 2021). "The levels of numerous proinflammatory cytokines are elevated by the JAK2/STAT3 pathway, and these cytokines play a crucial role in pathological injury in stroke." (PMID 34367186, 2021). "On the other hand, kaempferol glycosides suppress brain injury and inflammation by inhibiting the activation of NF-κB and STAT3 in stroke rats." (PMID 33727915, 2021). "At the transcriptional level, statins act on the geranylgeranyl pathway and decrease activation of the transcription factor STAT3, leading to the attenuation of inflammation and neuroprotection effects after stroke." (PMID 34489618, 2021). "Enhanced STAT3 activation is reported in ischemic tissue from a spectrum of ischemic diseases, including stroke and myocardial infarction, and functions as a protective factor to improve the recovery of these diseases." (PMID 35008699, 2021). "Conversely, STAT3 inhibition can reduce brain damage and improve neurological outcome in different stroke models 6-8." (PMID 33391532, 2021). "In this study, BV2 cells are substituted for microglia to obtain enough sEV, we found that sEVs derived from M2 BV2 cells reduced glial scar formation and improved neurological functional recovery after stroke via the miR-124/STAT3 signal pathway." (PMID 33391532, 2021). "Another important issue is that Raker’s study suggested that deletion of STAT3 exerts a neuroprotective role in stroke, which seems to conflict with the discovery that STAT3 activation enhanced A2-like astrocyte formation after reperfusion in this study." (PMID 34645472, 2021). "Activation of the JAK/STAT3 signaling pathway has been strongly correlated to the presence of reactive astrocytes in animal models of AD as well as stroke and epilepsy." (PMID 34911575, 2021).
Stroke (continued). "This presents an important step forward in understanding PDIA3 functions related to STAT3 signaling and new avenues for therapeutic intervention for diseases such as stroke." (PMID 34922569, 2021). "iMSC-sEV significantly upregulated the STAT3 signaling pathway in the peri-infarct area in rats after stroke and cultured HUVECs subjected to OGD in the present study." (PMID 32698909, 2020). "Here, we show for the first time that iMSC-sEV possess the potential to promote angiogenesis after stroke, at least in part, by inhibiting STAT3-dependent autophagy." (PMID 32698909, 2020). "We next used stattic, a STAT3 inhibitor, to further confirm the role of STAT3 in the preventative effects of iMSC-sEV on stroke-induced autophagy." (PMID 32698909, 2020). "Conditional knockout of endothelial STAT3 reduced angiogenesis and exacerbated neurological deficits after stroke, suggesting an important role of STAT3 in regulating angiogenesis." (PMID 32698909, 2020). "We have also recently demonstrated that STAT3 signaling is increased in innate immune subsets after stroke in humans." (PMID 32849569, 2020). "Our data further demonstrated that astrocytic ET-1 promoted proliferation of neural progenitor cells and their differentiation into astrocytes after stroke via the Jak2/Stat3 pathway and thus contributed to more severe brain damage after stroke." (PMID 31733648, 2019). "Taken together, these findings indicated that astrocytic endothelin-1 overexpression promoted neural progenitor cell proliferation and differentiation into astrocytes via the Jak2/Stat3 pathway in murine models of stroke." (PMID 31733648, 2019). "Previous studies have verified that STAT3 plays an essential role in various diseases, including cancers 16, myocardial ischemic injury 17, stroke 8, and obesity." (PMID 31588227, 2019). "This is further supported by the evidence that other substances that elevate STAT3 phosphorylation in neurons and astrocytes have been shown to exert neuroprotection in stroke models." (PMID 31849581, 2019). "Overactivation of p-STAT3 can contribute to the upregulation of proinflammatory cytokines under some kinds of stroke." (PMID 30126439, 2018). "Interleukin 6 is important for protection against detrimental effects and for recovery in a stroke mouse-model and activated STAT3 regulates Vascular endothelial growth factor expression (VEGF), a growth factor important for angiogenesis after stroke." (PMID 29518129, 2018). "In line with our results, many genes/proteins such as Hmox1, Gadd45, Ets-1, and Stat3 which are previously shown to be deregulated following stroke were also reported in our study." (PMID 29516010, 2018). "Expression of SCG2 is modulated by extracellular calcium, and it can induce expression of the anti-apoptotic protein Bcl2 through activation of JAK2/STAT3 signaling, providing protection in a murine stroke model." (PMID 30670947, 2018). "Although it is able to reduce the stroke-induced increase in pJAK3 and STAT3, downstream effectors of JAK3 activation, decernotinib is not neuroprotective in the acute phase of ischemic stroke." (PMID 28790974, 2017). "The STAT3 signaling pathway has been suggested to play a critical role in neuroinflammation and the activation of microglia following neurotoxic insults and stroke." (PMID 28923114, 2017). "It has been previously suggested that treatments with the ability to activate Stat3 expression have been found to improve behavioral functions and decrease cell death after stroke." (PMID 27683877, 2016). "In primary cortical neurons and murine models of stroke, the activation of STAT3 pathway by secretoneurin has been found to exert neuroprotective effects and induce neuronal plasticity after hypoxia and ischemic insult." (PMID 25946003, 2015).
Stroke (continued). "In primary cortical neurons and murine models of stroke, the activation of the Jak2/Stat3 pathway by secretoneurin has been found to exert neuroprotective effects and induce neuronal plasticity after hypoxia and ischemic insult." (PMID 25092271, 2014). "EPO and EPOR also induce neurogenesis after stroke, early during embryonic development and in vitro via Jak2/Stat3 and PI3K/AKT pathway activation." (PMID 21777449, 2011). "In addition, in future studies, analysis of the downstream pathways following STAT3 phosphorylation in astrocytes will provide more specific mechanisms to better understand the role played by astrocytes after stroke." (PMID 40919080, 2025). "Besides, overexpression of MANF induced neural stem cell differentiation, increased cell migration in SVZ explants, activated the STAT3 signaling pathway, and promoted endogenous repair after stroke." (PMID 40919080, 2025). "Clinical evidence shows that blood and cerebrospinal levels of IL6 are significantly elevated in patients following stroke; the JAK/STAT3 pathway is highly implicated in post-stroke inflammation by inducing the transcription of inflammatory mediators like cytokines and chemokines." (PMID 40362325, 2025). "Four hub PANRGs (MCL1, TNFRSF1A, STAT3, Hsp90aa1) were identified, enriched in MAPK and PI3K-AKT signaling pathways and negatively associated with oxidative phosphorylation, suggesting their involvement in stroke pathogenesis." (PMID 41235394, 2025). "Notably, increased activity for multiple of these TFs (e.g. Stat5a, Stat3, Myc, Hif1a, Snai1) was also observed in stroke-specific OPC and Oligodendrocyte subsets." (PMID 39043661, 2024). "Circ-STAT3 might be a predictor for stroke functional outcomes in 982 patients’ analysis for stroke recovery." (PMID 38515760, 2024). "In the M2 microglia, exosomal miR‐124 reduces the formation of glial scar after stroke by inhibiting the expression of signal transducer and activator of transcription 3 (STAT3), promotes poststroke recovery, and alleviates the migration and proliferation of astrocytes." (PMID 37313330, 2023). "Therefore, the regulation of overactivated STAT3 in microglia is essential to regulate microglial activation, ROS level and neuroinflammation, all of which are tightly related to neuron damage in stroke." (PMID 37063929, 2023). "Lastly, we predicted 53 potential drugs that may exert neuroprotective effects in early stroke by targeting 5 genes (STAT3, MMP9, AQP9, SELL, FPR1)." (PMID 37180174, 2023). "It has been reported that activation of the JAK2/STAT3 pathway could induce the production of IL‐6 and exacerbate stroke‐induced brain injury." (PMID 37143406, 2023). "In this study, our results showed that astrocytic IL-17A promoting post-stroke angiogenesis in enriched animals might be linked with the upregulation of IL-6, JAK2, and STAT3, and moreover, that this promoting effect was neutralized by anti-IL-17 mAb." (PMID 36873773, 2023). "To ascertain whether IL-13 suppressed the inflammatory response by inhibiting STAT3 activation in the stroke brain, we firstly assess that IL-13 whether directly inhibit the STAT3 activity in vitro using rat primary microglia culture." (PMID 35578342, 2022). "Recent studies have pinpointed the loss of NK cell effector function after stroke to reduced activity of the JAK/STAT3 pathway, since activation of this pathway specifically in NK cells after stroke successfully restored their function and reduced infection in an experimental animal model." (PMID 38566903, 2022). "Together our results suggest that STAT3 helps maintain the integrity of the blood–brain barrier and that its down-regulation during ischemic events contributes to pathological brain injury, identifying endothelial STAT3 as a potential therapeutic target in stroke." (PMID 36293020, 2022).
Stroke (continued). "EA pretreatment enhances STAT3 activation via CB1R to protect against cerebral ischaemia, suggesting that STAT3 activation may be a novel target for stroke intervention." (PMID 35463084, 2022). "To determine whether the endothelial dysfunction we observe in vitro upon pharmacological inhibition of STAT3 has functional relevance in vivo, we investigated the effect of reduced endothelial STAT3 on outcome after experimental stroke." (PMID 36293020, 2022). "suggest that circ-STAT3 may be a novel biomarker for predicting functional outcomes after stroke and an important factor in IS recovery." (PMID 36275741, 2022). "Inhibiting STAT3 phosphorylation can effectively improve the prognosis of stroke, suggesting that STAT3 activation to an inappropriately high level after focal ischemia might be detrimental." (PMID 35578342, 2022). "We also assessed the effects of STAT3 inhibition with stattic on sensorimotor and cognitive function to explore whether it mimicked the neuroprotective effects of IL-13 in stroke mice." (PMID 35578342, 2022). "Interestingly, in the recovery phase after stroke, endothelial STAT3 plays a role in promoting angiogenesis." (PMID 36293020, 2022). "Endothelial STAT3 may serve as a potential target in preventing endothelial dysfunction after stroke." (PMID 36293020, 2022). "Calpain-1-specific inhibitor PD151746 promoted phosphorylated signal transducer and activator of transcription 3 (p-STAT3) expression and was auxiliary to the proliferation and functional recovery of neural precursor cells in the subventricular zone after stroke." (PMID 36569944, 2022). "Interestingly, STAT3 activation during stroke was shown to exert pro-inflammatory and anti-inflammatory effects on different cell types and stages." (PMID 36506580, 2022). "However, although global pharmacological inhibition of STAT3 is detrimental in stroke, activation of STAT3 in some cell types, specifically microglia, can result in detrimental outcomes following MCAO." (PMID 36293020, 2022). "Finally, the phosphorylation status of STAT3 (p-STAT3, Tyr705) was tested in the brains of stroke animal models using western blot analysis." (PMID 36446389, 2022). "The results show that circ-STAT3 may be a new biomarker to predict the functional outcome after stroke and is also an important factor in the recovery of IS." (PMID 35371609, 2022). "In addition, the Janus kinase 2/signal transducer and activator of transcription 3 (JAK2/STAT3) pathway is known to be abnormally activated in stroke, and this combination treatment appears to decrease this abnormal activation." (PMID 34944727, 2021). "In addition to KLF9, we also identified STAT3 as varying significantly over space, which was also an enriched GO term in stroke cells." (PMID 33627658, 2021). "It has been shown that resveratrol, a naturally occurring polyphenolic compound, modulates microglial activity, exhibits neuroprotective effects, and improves stroke outcome through the regulation of TLR4/NF-kB/ signal transducer and activator of transcription 3 (STAT-3) signaling pathway." (PMID 34200356, 2021). "Stat3 has been shown to be activated in in vitro and in vivo experimental models of stroke and promotes transcriptional upregulation of numerous genes that may play a critical role in both neural injury and repair." (PMID 34943061, 2021). "Indeed, the effect of STAT3 activation on other aspects such as neuronal death and neuroinflammation after stroke is still in debate." (PMID 32698909, 2020). "A main component of SCFA-sodium butyrate through its HDAC-inhibiting ability can promote the expression of anti-inflammatory (IL-10) genes and the downstream IL-10/STAT3 pathway in microglia, which can positively promote neurogenesis and axonal growth after a stroke insult." (PMID 33042113, 2020). "The role of STAT3 signaling pathway on brain vessel after stroke is multifaceted." (PMID 32698909, 2020).